MTOR (mechanistic target of rapamycin kinase)
Diseases named in the same sentence as MTOR in open-access papers (continued):
Sharing a sentence is not in itself a finding about the gene and the disease.
neurological disorders (continued). "Interestingly, the observed hyperactivation of mTOR is a hallmark of epileptic neurological disorders." (PMID 33888873, 2021). "Targeting Unkempt may therefore be a novel therapeutic strategy for neurological diseases associated with activated mTOR signaling." (PMID 34381067, 2021). "Here, we provide a brief review of mTOR changes in the brain that are associated with some neurological disorders and focus on how these changes may be relevant to the pain of the underlying condition and chronic pain itself." (PMID 31194026, 2018). "Altered mTOR signalling is associated with brain malformation and neurological disorders." (PMID 30061532, 2018). "Importantly, aberrant expression of TSC1 or TSC2 causes significant neurological disease, and overactivation of mTOR has been linked to the development of neurodegenerative disorders." (PMID 28732515, 2017). "These emerging studies suggest that mTOR signaling may facilitate developmental processes specific to human cortical development but also, when mis-regulated, cause cortical malformations and neurological disease." (PMID 36226315, 2022). "Since deregulation of the mTOR is linked to several neurological diseases, including ASD as well as its activation leads to Tau dyshomeostasis by regulation Tau synthesis, phosphorylation, and degradation, we investigated whether prenatal exposure to VPA affects mTOR activity." (PMID 33809910, 2021). "Since mTOR is a major regulator of aging, we propose that mTOR-dependent age-associated brain vascular dysfunction may be a central mechanism linking aging to the pathogenesis of AD and potentially other age-associated neurological diseases." (PMID 32756010, 2020). "Our results provide novel and fundamental molecular bases for understanding hyperactivated mTOR signaling-induced brain defects which can in turn facilitate identification of potential diagnostic markers and therapeutic targets for mTOR signaling-related neurological disorders." (PMID 28588230, 2017). "Several PI3K and mTOR inhibitors have been explored for their anti-inflammatory effects in neurological disorders." (PMID 40427570, 2025). "Considering that signalling through the mTOR pathway has been related to rapid aging, progression of neurological diseases, as well as T2DM our results would support a beneficial role of metformin." (PMID 39170185, 2024). "Curcumin has been known to have great therapeutic efficacy in treating neurodegenerative and neurological diseases because of its anti-oxidant, anti-inflammatory, and mTOR-inhibiting properties." (PMID 38296969, 2024). "The mTOR network comprises several crucial molecular targets that have been identified as53 potential therapeutic targets for various neurological disorders." (PMID 37721413, 2024). "This review covers genetic aspects of TSC, the role of the mTOR signaling pathway in TSC pathogenesis, and the origin of cortical tubers, their histopathology, and their association with neurological diseases." (PMID 37232723, 2023). "The excess of mTOR signalling in the brain highlights a potential link between mTOR and neurological disease in humans." (PMID 37550884, 2023). "The disturbance of mTOR signaling plays a key role in a variety of neurological disorders, including TSC, FCD, hemimegalencephaly, epilepsy, and autism spectrum disorder." (PMID 37232723, 2023). "In contrast to belatacept and basiliximab, long-term CNI-free therapy based on mTOR inhibitors has an acceptable safety profile with functional improvements of patients with neurological diseases." (PMID 37200246, 2023). "In the present systematic review, we highlight the potential therapeutic effects of exosomes in the context of NDDs and neurological diseases by targeting the PI3K/Akt/mTOR signaling pathway." (PMID 36986865, 2023). "There is abundant evidence linking mTOR signalling to synaptic change, memory and neurological disease." (PMID 37550884, 2023).
neurological disorders (continued). "This is the first systematic review that critically highlights the modulatory effects of exosomes as effective/safe drug delivery vehicles in the context of neurological diseases through PI3K/Akt/mTOR pathway." (PMID 36986865, 2023). "These landmark articles provide readers with an authoritative understanding of the current mechanism of action of mTOR in neurological disorders and its potential applications." (PMID 36118114, 2022). "Although these drugs are primarily approved for the treatment of diabetes, various recent studies have investigated their use in neurological diseases by virtue of their modulatory effect on the mTOR signaling pathway." (PMID 35744783, 2022). "Since these pioneering studies, mTOR signaling has been shown to regulate many aspects of nervous system development, and to be involved in numerous neurological disorders." (PMID 36226315, 2022). "Mammalian target of rapamycin (mTOR) signaling is crucial for neuronal growth, development, apoptosis, and autophagy, but the dysregulation of mTOR signaling leads to neurological disorders." (PMID 34784444, 2022). "This information should be carefully considered when using the results to discuss the role of the mTOR pathway in neurological disease." (PMID 35211177, 2022). "This study aimed to present the current study hot spots and predict the future development trend of the mTOR pathway in neurologic diseases using bibliometrics." (PMID 36118114, 2022). "A dysregulated mTOR pathway is included in many pathological conditions including neurological disorders, metabolic diseases, epilepsy, and autism." (PMID 35744783, 2022). "The loss-of-function of negative regulators of mTOR triggers behavioral abnormalities and neurological diseases by over-activating mTOR signaling." (PMID 34309811, 2021). "Nevertheless, the molecular functions of newly-identified negative regulators of mTOR in the occurrence and development of neurological diseases remain elusive." (PMID 34309811, 2021). "Synaptogenesis-related signaling molecules such as Akt/mTOR were then examined as their activities are involved in various neurological disorders including MDD." (PMID 33526073, 2021). "Due to the importance of autophagy and apoptosis in neurological diseases, as well as differences in mTOR and FoxO3a activity levels in the sexes, we decided to analyze the expression profile of key autophagic and apoptotic proteins." (PMID 33214645, 2020). "Impaired mTOR activity has been involved in age-related diseases, and neurological disorders, including neurodegenerative diseases." (PMID 32051464, 2020). "Our study therefore illustrates that mTOR is a critical regulator of motor abnormalities in neurological disorders and the translational potential of rapamycin in alleviating striatal D2R-mediated EPS in humans." (PMID 33009372, 2020). "mTOR hyperactivation has been found to be active in many types of human cancers and neurological disorders." (PMID 31133639, 2019). "The intervention of the mTOR signaling pathway by precise application of small molecular inhibitors will benefit both lifespan and neurological disorders." (PMID 29772672, 2018). "The Akt/mTOR signaling pathway is a central axis in the regulation of cellular processes, particularly in neurological diseases." (PMID 29883380, 2018). "The dysregulation of mTOR in a wide array of neurological disorders highlights the complexity of this signaling pathway and suggests that normal mTOR activity is essential for optimal health." (PMID 31194026, 2018). "U-87MG cells are commonly used as a model to study neurological diseases, characterized by an up-regulation of mTOR (molecular target of rapamycin), an important inhibitor of autophagy." (PMID 29311919, 2017). "Dysregulation of the mTOR pathway has been implicated in the development of many cancers, including TSC, along with other neurologic disorders." (PMID 28288694, 2017).
neurological disorders (continued). "Akt and mTOR are essential homeostatic components that are altered during chronic (AD) or acute (CI) neurological disease." (PMID 26042033, 2015). "Such a result would support the view that perturbation of the mTOR signaling cascade is a common pathophysiological feature of human neurological disorders, including mental retardation syndromes and ASDs." (PMID 24517317, 2014). "It has been shown that PKCγ is upstream of several signaling pathways, including ERK and the mammalian target of rapamycin (mTOR), which are involved in several neurological disorders, including AD." (PMID 24421757, 2013). "Regarding neurological disorders, mTOR is a promising therapeutic target as well." (PMID 38164133, 2023). "Given the contribution of the mTOR pathway to nervous system development and disease pathogenesis, miRNA-mediated regulation of the mTOR pathway may play a critical role in brain development and various neurological disease states." (PMID 36824367, 2023). "It is worth mentioning that various types of exosomes could ameliorate several other neurological diseases via the PI3K/Akt/mTOR pathway and other interconnected signaling pathways." (PMID 36986865, 2023). "Therefore, controlling the mTOR signaling pathway can change the processes related to inflammation, apoptosis, and autophagy in nervous system diseases." (PMID 35669881, 2022). "Thus, inhibiting mTOR through dietary modification (i.e., IF) seems a promising prospect for these neurologic disorders." (PMID 35334932, 2022). "The regulation of the mTOR signaling pathway is important in nervous system diseases." (PMID 35669881, 2022). "Moreover, future studies are needed to further clarify the contributions of each mTOR complex to these neurological diseases." (PMID 32125271, 2020). "Thus, mTOR-driven cerebrovascular dysfunction may represent an early and possibly universal feature of aging that underlies cognitive impairment and the increased susceptibility of the elderly to specific forms of neurological disease, including but not limited to AD and related dementias." (PMID 32756010, 2020). "Together, these data suggest that complex specific targeting may be necessary to restore normal synaptic function in neurological diseases involving mTOR hyperactivation." (PMID 32125271, 2020). "In addition, perturbation of the mTOR signaling cascade appears to be a common pathophysiological feature of human neurological disorders." (PMID 32198387, 2020). "Although mTOR signaling is known as a broad regulator of cell growth and proliferation, in neurons it regulates synaptic transmission, which is thought to be a major mechanism through which altered mTOR signaling leads to neurological disease." (PMID 32125271, 2020). "mTOR signaling is also involved in the regulation of immune reactions in many neurologic diseases." (PMID 33153476, 2020). "Therefore, perturbation of mTOR signaling cascade appears as a common pathophysiological feature of human neurological disorders." (PMID 32443912, 2020). "Since dysfunctional mTOR signaling is found in a wide array of brain disorders that have pain as a comorbidity, we examine various neurological disorders where mTOR changes in the brain are well-documented and highlight the implications of these changes for understanding pain." (PMID 31194026, 2018). "•mTOR signalling in the brain as a pathology for neurological disorder is known." (PMID 31194026, 2018). "Not surprisingly, dysregulation of mTOR signaling is implicated in diverse neurological disorders encompassing developmental, degenerative and psychiatric types." (PMID 28588230, 2017). "Such successful dissection of the molecular nature of TSC may also facilitate identification of therapeutic options for multiple mTOR signaling-related neurological disorders." (PMID 28588230, 2017).
neurological disorders (continued). "In sum, this study establishes fundamental molecular bases for phenotypic aberrations caused by hyperactivated mTOR signaling in the brain, which can be useful for isolation of biomarkers and/or therapeutic targets of mTOR signaling-related neurological disorders." (PMID 28588230, 2017). "mTOR is an important drug target in multiple neurological disorders." (PMID 27380875, 2016). "Therefore, mTOR is a promising target for the treatment of psychiatric and neurological disorders." (PMID 38365306, 2024). "However, also other, so far unknown, mechanisms most likely result in dysregulated mTOR signaling in the context of neurological disorders." (PMID 39652154, 2024). "Besides, AIMTOR could help phenotyping mTOR signaling in neurological disorders, as we did for Shank3Δ11 mice." (PMID 32620110, 2020). "In addition to furthering research of mTOR inhibition in rare neurologic disorders, future research will also focus on defining the optimal use of mTOR inhibitors in TSC, including dosages for short- and long-term use, as well as age at which to initiate therapy." (PMID 28288694, 2017). "However, available results in these areas show promise that, after further research, mTOR inhibition may eventually become a therapy option for these neurologic disorders where few options are currently available." (PMID 28288694, 2017). "In other neurological diseases, a study revealed that AKT/mTOR contributed to ROS production to exacerbate necroptosis in the mouse hippocampal neuronal cell line HT-22." (PMID 38164133, 2023). "In neurological diseases, TNF-α inhibits microglial autophagy via the Akt/mechanistic target of rapamycin (mTOR) pathway, which aggravates neuroinflammation." (PMID 34899367, 2021). "Our results supported our hypothesis that the GES-guided drug–disease association method is better suited for some subgroups or pathways such as drugs and diseases associated with the immune system, diseases of the nervous system, non-chemotherapy drugs or the mTOR signaling pathway." (PMID 32560162, 2020). "Most notably, a recent study pointed out that GC fragmentation associated with slight overexpression of Golgin GCC88 decreases mTOR activity and increases autophagy in HeLa cells, suggesting that disruption of GC morphology could lead to reduced mTOR activity in neurological disorders." (PMID 31134199, 2019). "As mTOR controls several nervous system functions such as development, plasticity, memory, and cognition, it is no surprise that neurological disorders such as FXS report abnormal mTOR signaling." (PMID 35456004, 2022). "Our previous studies showed that UBTOR/KIAA1024/MINAR1 acts as a negative regulator of mTOR signaling, but whether UBTOR plays a role in neurological diseases remains largely unknown." (PMID 34309811, 2021). "Because mTOR is involved in diverse phenomena, such as autophagy, cell proliferation, and cell motility, its regulation by REDD1 has the potential to be a pharmacological target for various neurological diseases." (PMID 33322202, 2020). "This study, along with earlier observations regarding sphingolipid effects on established mTOR functions, therefore provides a previously unknown connection between the regulation of mTORC2 activity by PIP3 within LRs and a genetic nervous-system disease." (PMID 31036560, 2019). "This review has touched upon some – but by no means all – of the neurological diseases that exhibit changes in mTOR-related brain activity." (PMID 31194026, 2018). "Here, we review the different PIDs that share an impairment of the PI3K/AKT/mTOR/S6K pathway and we propose to name them “immune TOR-opathies” by analogy with a group of neurological disorders that has been originally defined by PB Crino and that are due to aberrant mTOR signaling." (PMID 29867948, 2018).
neurological disorders (continued). "Thus, IGF-1 is a promising therapeutic option for the treatment of various neurological disorders through regulation of multiple neuroprotective signaling pathways, including Ras/Erk1/2, PI3K/MAPK/Akt/mTOR, Ca2+/CaMK II and IV, CREB, C/EBPβ, and GSK3B/NF-kB/NLRP3." (PMID 36691085, 2023). "In LHQW, arctiin, corymbosin, and aloe-emodin target neurological disease-related genes (GRM1 and GRM5), whereas in QFPD, isofucosterol, baicalein, nobiletin, oroxylin A, epiberberine, and piperlonguminine target immunity- and inflammation-related genes (mTOR and PLA2G4A)." (PMID 36210820, 2022). "Moreover, the common Wnt/mTOR pathways that have been altered both in ADHD and AD, and the fact that some drug treatments may influence them, should be studied more in-depth, to explore the possibilities of prevention and/or rescue in these two frequent neurological disorders." (PMID 36875654, 2023).